BTBD10 (BTB domain containing 10)
Description:
Plays a major role as an activator of AKT family members by inhibiting PPP2CA-mediated dephosphorylation, thereby keeping AKTs activated. Plays a role in preventing motor neuronal death and accelerating the growth of pancreatic beta cells.
Synonyms: GMRP1; GMRP-1; MGC13007
Tractability: PROTAC: ubiquitination databases record sites on it.
Gene: Protein-coding gene on chromosome 11 (13,388,004 to 13,464,029, reverse strand). Ensembl gene ENSG00000148925.
Subcellular location: Nucleus; Cytoplasm
Subcellular location (Human Protein Atlas): Nucleoli fibrillar center; Nucleoplasm; Plasma membrane
Gene Ontology:
Molecular function: protein binding
Biological process: positive regulation of phosphatidylinositol 3-kinase/protein kinase B signal transduction; type B pancreatic cell proliferation
Cellular component: fibrillar center; nucleoplasm; cytoplasm; nucleus
Genetic constraint (gnomAD): Loss-of-function variants: 15 observed, 39.34 expected, observed/expected ratio (o/e) 0.38, 90% interval 0.25 to 0.59. The synonymous counts are far from expectation, so gnomAD's model fits this gene poorly and the ratio says little. Missense variants: 301 observed, 503.82 expected, observed/expected ratio (o/e) 0.6, 90% interval 0.54 to 0.66. Synonymous variants: 129 observed, 166.36 expected, observed/expected ratio (o/e) 0.78, 90% interval 0.67 to 0.9.
Homologues: Orthologues: chimpanzee BTBD10 (100% identical), macaque BTBD10 (99% identical), dog BTBD10 (98% identical), rabbit BTBD10 (98% identical), guinea pig Btbd10 (92% identical), mouse Btbd10 (91% identical), rat Btbd10 (91% identical), tropical clawed frog btbd10 (86% identical), zebrafish btbd10a (79% identical), zebrafish btbd10b (79% identical), Caenorhabditis elegans btbd-10 (48% identical), Drosophila melanogaster mri (47% identical). Paralogues in human: KCTD20 (53% identical).
Diseases named in the same sentence as BTBD10 in open-access papers:
BTBD10 is named in the same sentence as 14 diseases in open-access papers, as found by Europe PMC text mining. Sharing a sentence is not in itself a finding about the gene and the disease. The quoted sentences say what the papers report.
hepatocellular carcinoma (4 papers, 2021 to 2024). A malignant tumor that arises from hepatocytes. "Studies have reported that BTBD10 is a prognostic biomarker in cancer and associated with immune infiltration such as glioma, and hepatocellular carcinoma." (PMID 38835051, 2024). "Additionally, the expression of BTBD10 was increased in hepatocellular carcinoma tissue, and a higher level of BTBD10 was associated with a poorer prognosis." (PMID 36045715, 2022). "BTBD10 functions as an activator of AKT family members by inhibiting PPP2CA-mediated dephosphorylation, and a few studies have identified it as a prognostic risk factor in hepatocellular carcinoma and glioma." (PMID 37007130, 2023). "The present study attempted to investigate the prognostic value of BTBD10 in hepatocellular carcinoma (HCC), specially, its relationship with tumor-infiltrating lymphocytes (TILs)." (PMID 35059434, 2021). "Interestingly, BTBD10 was not differentially expressed in hepatocellular carcinoma, ovarian cancer, or lung cancer, which suggests that BTBD10 may be specifically linked to glioma." (PMID 36045715, 2022).
glioma (3 papers, 2022 to 2024). A benign or malignant brain and spinal cord tumor that arises from glial cells (astrocytes, oligodendrocytes, ependymal cells). "In this study, we examined the expression of BTBD10 in glioma and normal brain tissue obtained from patients who had undergone surgery." (PMID 36045715, 2022). "The mRNA and protein levels of BTBD10 in 52 glioma tissues and eight normal brain tissues were determined using reverse transcription polymerase chain reaction (RT-PCR) and western blot analysis, respectively." (PMID 36045715, 2022). "The RT-PCR data revealed that BTBD10 mRNA expression was highest in normal brain tissue (1.07 ± 0.54), intermediate in low-grade glioma tissue (0.57 ± 0.23) and lowest in high-grade glioma tissue (0.19 ± 0.10; P = 0.037 and P = 0.003, respectively)." (PMID 36045715, 2022). "BTBD10 is downregulated in human glioma, and the expression of BTBD10 is negatively correlated with the pathological grade of the tumor." (PMID 36045715, 2022). "By contrast, the present study demonstrated that p-Akt levels were decreased in U251 cells overexpressing BTBD10, implying that BTBD10 is a negative regulator of the Akt signaling pathway in glioma cells." (PMID 36045715, 2022). "The results showed that BTBD10 mRNA and protein levels were significantly lower in glioma tissues than in normal brain tissues." (PMID 36045715, 2022). "In this study, we confirmed that BTBD10 is downregulated in human glioma tissue at both the mRNA and protein levels." (PMID 36045715, 2022). "Furthermore, we evaluated the relationship between tumoral BTBD10 expression and clinicopathologic characteristics (including the pathological grade and type of glioma and the age and gender of the patient)." (PMID 36045715, 2022). "However, the detailed mechanisms by which BTBD10 downregulates cyclin D1 and p-Akt in glioma cells will require further investigation." (PMID 36045715, 2022). "Thus, the anti-tumorigenic effects of BTBD10 overexpression in glioma cells were likely mediated, at least in part, by cyclin D1- and Akt-dependent signaling pathways." (PMID 36045715, 2022). "Additionally, BTBD10 levels were significantly lower in high-grade gliomas than in low-grade tumors." (PMID 36045715, 2022). "The aim of this study was to investigate the role of BTBD10 in glioma tumorigenesis." (PMID 36045715, 2022). "Although these findings implicated BTBD10 in the pathogenesis of glioma, further evidence to support this possibility has not yet been reported." (PMID 36045715, 2022). "Our findings that BTBD10 was downregulated in human glioma tissue and that BTBD10 overexpression exerted anti-proliferative effects in U251 cells do not agree with these previous reports, which suggests that the functional effects of BTBD10 in glioma cells may differ from those in other cell types." (PMID 36045715, 2022). "Thus, BTBD10 may play a unique role in the pathogenesis of glioma." (PMID 36045715, 2022).
amyotrophic lateral sclerosis (2 papers, 2022 to 2024). Amyotrophic lateral sclerosis (ALS) is a neurodegenerative disease characterized by progressive muscular paralysis reflecting degeneration of motor neurons in the primary motor cortex, corticospinal tracts, brainstem and spinal cord. "Furthermore, a decrease in BTBD10 expression has been linked to motor neuron death in cases of amyotrophic lateral sclerosis cases due to the downregulation of the AKT-mediated prosurvival signal." (PMID 38835051, 2024). "Previous in vitro studies have indicated that downregulation of BTBD10 promotes neuronal death and may contribute to the pathogenesis of amyotrophic lateral sclerosis and brain damage after intracerebral hemorrhage." (PMID 36045715, 2022).
glioblastoma (1 paper, 2022). The most malignant astrocytic tumor (WHO grade IV). "We also investigated the effects of BTBD10 overexpression on the growth and apoptosis of a human glioblastoma cell line and explored the signaling pathways that mediated these effects." (PMID 36045715, 2022). "In line with these clinical data, overexpression of BTBD10 inhibited the proliferation and promoted the apoptosis of U251 human glioblastoma cells in vitro." (PMID 36045715, 2022). "Furthermore, BTBD10 overexpression inhibits proliferation, induces G0/G1 arrest, and promotes apoptosis in human glioblastoma cells by downregulating cyclin D1- and Akt-dependent signaling pathways." (PMID 36045715, 2022). "Furthermore, BTBD10 overexpression inhibits proliferation, induces G0/G1 arrest, and promotes apoptosis in human glioblastoma cells by downregulating cyclin D1 and attenuating Akt signaling." (PMID 36045715, 2022). "U251 human glioblastoma cells were infected with BTBD10-expressing or control lentiviruses." (PMID 36045715, 2022).
non-small cell lung (NSCLC) cancer (1 paper, 2021). "The BTBD10 subunit (KCTD20) enhanced the proliferation and invasion of non-small cell lung (NSCLC) cancer by increasing the phosphorylation level of Akt." (PMID 35059434, 2021).
Salmonella Infections (1 paper, 2011). Infections with bacteria of the genus SALMONELLA. "Other top-ranked differentially expressed genes in the LS1 pigs such as KRTAP11-1, TAF1B and BTBD10, have not been associated with Salmonella infection previously." (PMID 22174891, 2011).
cancer (3 papers, 2022 to 2024). A tumor composed of atypical neoplastic, often pleomorphic cells that invade other tissues. "Only a limited number of published reports have examined the role of BTBD10 in cell proliferation or cancer." (PMID 36045715, 2022). "BTBD10 (43%), PLCD3 (27%), and RFX3 (24%) were frequently mutated in pan-cancer." (PMID 37007130, 2023).
tumor (2 papers, 2021 to 2022). "we confirmed that BTBD10 was associated with tumor clinical stage and pathological grade and can serve as an independent prognostic risk factor for HCC patients." (PMID 35059434, 2021). "Specially, BTBD10 has been found to be associated with tumor progression." (PMID 35059434, 2021). "Our results showed that the expression of BTBD10 promoter methylation in tumor tissues was lower than that in normal tissues, and the level of BTBD10 promoter methylation gradually decreased with the increase of tumor grade." (PMID 35059434, 2021). "According to the prediction of TIMER data, the expression of BTBD10 mRNA in 11 types of tumor tissues (including HCC tissues) was significantly higher than that in normal tissues." (PMID 35059434, 2021). "Recently, scientists found that KCTD20) enhanced the proliferation and invasion of NSCLC via increasing the phosphorylation level of Akt, indicating a potential role of BTBD10 in tumor diseases." (PMID 35059434, 2021). "Our study unraveled that BTBD10 was high expressed in HCC tumor and showed an adverse impact on the prognosis of patients with HCC." (PMID 35059434, 2021). "Our data suggested that high expression of BTBD10 significantly affected immune response-related pathways, which could reveal the mechanism by which tumor cells evade immune response." (PMID 35059434, 2021). "Furthermore, BTBD10 expression was demonstrated to be positively correlated with tumor-infiltrating B cells, T cells, macrophages, neutrophils and dendritic cells." (PMID 35059434, 2021). "In addition, we detected a negative association between tumoral BTBD10 expression and the pathological grade of the tumor, which suggests that BTBD10 may act as a tumor suppressor during disease progression." (PMID 36045715, 2022). "BTBD10 interferes with TME homeostasis by affecting the composition ratio of TILs, and this “two-way communication” information exchange promotes tumor progression and metastasis." (PMID 35059434, 2021). "Analyses of data obtained from TIMER and TCGA data showed that BTBD10 was positively correlated with B cells, CD4+ T cells, CD8+ T cells, macrophages, DCs and neutrophils in the tumor." (PMID 35059434, 2021). "Subsequently, the Tumor Immune Dysfunction and Exclusion (TIDE) algorithm revealed that the response to ICIs was poorer in the high BTBD10 expression group than in the low BTBD10 expression group (high TIDE score, worse response to ICIs, and short survival after ICIs treatment)." (PMID 35059434, 2021).
BTBD10 also shares sentences with these, for which no sentence is quoted: breast invasive carcinoma (1 paper); intracerebral hemorrhage (1); lung carcinoma (1); lung squamous cell carcinoma (1); ovarian carcinoma (1); progressive myoclonus epilepsy (1).